CTSD (cathepsin D)
Diseases named in the same sentence as CTSD in open-access papers (continued):
Sharing a sentence is not in itself a finding about the gene and the disease.
cancer (continued). "Additionally, blocking MMP-2, cathepsin D, PAI-1, and Gal-1also reduced cancer cell invasion." (PMID 32984024, 2020). "However, cathepsin D expression in cells from the MTB was highly elevated in late stage CRC and showed significant correlation with subsequent distant metastasis and shorter cancer-specific survival." (PMID 22919486, 2012). "The results added, probably for the first time, that TCA-induced HCC through disruption of hepatocellular proteolytic enzymes as upregulation of papain, free cathepsin-D and nonsignificant destabilization of lysosomal membrane integrity, a prerequisite for cancer invasion and metastasis." (PMID 21994869, 2011). "As expected, cathepsin D silencing also stimulated the expression of ZO-1 and suppressed the level of N-cadherin, demonstrating that cathepsin D, as an independent marker of poor prognosis, could activate EMT, and in turn, induce cancer relapse and metastasis in luminal B subtype patients." (PMID 32846884, 2020). "For CTSL and CTSD, there is no direct evidence available for the effect of genetic variations in HCC or cancer in general." (PMID 36289617, 2022). "Immunohistochemistry of adjacent sections for CD45, a leukocyte common antigen, confirmed that cells staining for high levels of cathepsin D also stained for CD45, confirming that they were leukocyte phenotype rather than cancer cells." (PMID 22919486, 2012). "Our results suggest that radiation-induced increases of FN1, CTSD, GSN, and MRC2 may play radioresistant and negative roles in cancer therapy." (PMID 26056562, 2015).
infection (54 papers, 2008 to 2026). The state of being infected such as from the introduction of a foreign agent such as serum, vaccine, antigenic substance or organism. "The association with cathepsin D peaked 30 min post infection at 34.07 ± 14.58%, and at 2 h post infection the association with cathepsin D still represented 20.20 ± 6.75%." (PMID 26161475, 2015). "IgG responses to whole parasite lysate and MSP121 protein were measured in plasma from infected wildtype or cathepsin D deficient chimeric mice at day 36 post infection." (PMID 22053177, 2011). "Moreover, immunofluorescent staining for CTSD showed higher co-localization between CTSD and bacteria in wt macrophages after 1 h infection than in infected Asm-deficient macrophages." (PMID 33153072, 2020). "In comparison, cathepsin D mRNA levels increased in wild-type RAW cells 20 h post-infection with either stationary or late-log Salmonella." (PMID 38051049, 2024). "This gradual dispersal of CTSB and CTSD with infection time was also observed in NDV-infected A549 cells." (PMID 38354122, 2024). "It was demonstrated that pretreatment of HIV strains with cathepsin D not only enhanced infection of CD4+ T-lymphocytes but also allowed infection of epithelial CD4-negative cells." (PMID 34421929, 2021). "After 6 h of infection, S. aureus was also detected in cathepsin D-positive phagosomes of both CAP-treated and untreated macrophages." (PMID 34133202, 2021). "Then, we analyzed the lysosome function by detecting the lysosome proteins cathepsin B (CTSB) and cathepsin D (CTSD) via western blotting, and found that CTSB and CTSD were increased after infection, which was almost abolished by Tas2r138 knockdown." (PMID 34083514, 2021). "Similar to previous findings from mammalian host cell systems, A. baumanni resided in lysosomal marker LAMP-1 or cathepsin D-positive compartments at later time points post-infection (24 h.p.i.)." (PMID 32528902, 2020). "The immunoblot results demonstrated that infection with virulent H37Rv led to the processing of procathepsin D to mature cathepsin D (cleaved cathepsin D) in BALB/c and C57BL/6 BMDMs that were infected with virulent H37Rv." (PMID 27148227, 2016). "R. montanensis-positive staining is mostly co-localized with cathepsin D 24 h after infection, and this is further corroborated by the fluorescence intensity profiles showing substantial overlapping between signals." (PMID 27525249, 2016). "Using confocal microscopy, we showed that pre-treatment of macrophages with ant-328 increased expression of the lysosomal enzyme, Cathepsin D (increased red fluorescence in cytoplasm), following NTHi infection compared to Scr control treated macrophages." (PMID 25894560, 2015). "At 1 hour after infection, 28.4±8% of phagosomes containing T. whipplei acquired cathepsin D. This percentage increased, reaching a maximum value after one day (82±7%)." (PMID 24586722, 2014). "Lysozyme, cathepsin D, a nitrophorin-like protein and a putative 14 kDa protein were significantly upregulated upon infection, whereas thioredoxin reductase was downregulated." (PMID 23658688, 2013). "We sought to inhibit the fusion of lysosomes with the bacteria or the activation of cathepsin D by incubating pG-treated infected cells with NH4Cl or bafilomycin A1, prior and during infection and pG treatment." (PMID 24376710, 2013). "We examined co-localization of the phagosomes with the late endosomal/lysosomal marker LAMP-2 and the lysosomal marker cathepsin D at 30 min and 2 h after infection." (PMID 20552012, 2010). "Upon infection, M. bejeranoi deploys an array of activated proteases, including cathepsin D and cathepsin L, which may act to degrade hemoglobin, as in other parasites." (PMID 38891869, 2024). "After knockout of CTSD from Eriocheir sinensis (H. Milne Edwards) with RNAi, the expression levels of many immune-related genes were decreased, and the mortality was increased after infection with Spiroplasma eriocheiris Wang." (PMID 36896191, 2023).
infection (continued). "Stefin and cathepsin D were upregulated at all time points in IIR infections." (PMID 35071050, 2021). "We speculate that this might be the cause of the corresponding reduction in the expression level of CTSD in the early stage of infection." (PMID 33468223, 2021). "In addition, we also found that the levels of mature/activated form of cathepsin D increased in Rab35 knockdown cells with the progression of infection." (PMID 26248231, 2015). "To address this, we utilized an antibody that recognizes only the active form (24 to 30 kDa) of cathepsin D. Treatment with IL-12 and sIL-27R enhanced association of active cathepsin D with BCG phagosomes by approximately 85%, as compared with 3.6% during infection alone." (PMID 24618498, 2014). "We could not detect colocalization with the late lysosomal markers LAMP1 and cathepsin D, or with the early endosomal marker Rab5 after 24 h of infection." (PMID 23862148, 2013). "Mice that had undergone bone marrow transplantation with cathepsin D−/− bone marrow were significantly impaired in their capacity to clear low inocula of bacteria from the lungs, in a model of subclinical infection in which alveolar macrophages ensure bacterial clearance and mouse survival." (PMID 21298030, 2011). "At day 6 post-infection, more than 80% of organisms co-localized with both cathepsin D and Lamp-1." (PMID 21179488, 2010). "However, interestingly, when the RAW264.7 cells were infected with Y. pestis strain 201, both the basal expression of CTSD and those after infection were quite low compared with that of the U937 cells, indicating that very low expression of this protease occurred under these conditions." (PMID 31069175, 2019). "Second, the mRNA levels of LAMP1, cathepsin D, and LC3 all behaved distinctly depending on infection, time, and genotype." (PMID 38051049, 2024). "At 24 h post-infection, R. montanensis cells appear fragmented and co-localized with markers of lysosomal compartments, LAMP-2, and Cathepsin D, within PMA-differentiated THP-1 cells." (PMID 33669499, 2021). "We focused on mouse macrophages between 24 and 74 h after infection, using confocal microscopy coupled with staining for markers for the endosomal (EEA1 and LAMP1), autophagic (LC3B), and lysosomal (Cathepsin D and Lysotracker) pathways." (PMID 32694562, 2020). "GFP-LVS-infected macrophages in the presence of naïve or LVS-immune lymphocytes 48 h after infection were stained with markers of the endosomal (EEA1 and LAMP1), lysosomal (Cathepsin D and Lysotracker), and autophagic pathways (LC3B)." (PMID 32694562, 2020). "Concordant with these results, recruitment of Cathepsin D, a lysosomal hydrolase, in phagosomes was significantly impaired at 4 h of BMDM infection with R. oryzae as compared to A. fumigatus." (PMID 30127354, 2018). "The infected hMDMs were fixed at 2 h post-infection and labeled with antibodies specific for the late endosomal/lysosomal marker, LAMP2, and lysosomal enzyme, cathepsin D, and the ER marker, KDEL." (PMID 28321389, 2017). "We analysed two phagosome markers (LAMP-3 and Cathepsin D) and a marker for autophagy (LC3-II) in macrophages following L. major (GFP-IL81) infection." (PMID 27632901, 2016). "At 30 min after infection, ∼65% of the iglC mutant-containing phagosomes co-localized with LAMP-2 and cathepsin-D, as previously shown." (PMID 20552012, 2010). "The cells were then washed and further incubated in the presence of a bacteriostatic concentration of Polymyxin B. At 6, 24, or 48 h points post-infection bacterial colocalization with late endosomal (LAMP-1) and lysosomal (cathepsin D) markers was investigated." (PMID 38011105, 2023). "At 1 h after infection, a third of the phagosomes were positive for cathepsin D, irrespective of CAP treatment." (PMID 34133202, 2021).
infection (continued). "The specific genes in the geneset that associated with the greatest odds of reduced risk of infection including SEMA4A, CTSD, CD68, and GAA were all members of this pathway, but not TNFSF13 (APRIL) which was the most protective gene in the NHP studies." (PMID 34533134, 2021). "Unlike stefin, cathepsin D and aminopeptidase-N, both cysteine proteases were highly expressed by genotype 0 throughout the infection, with the highest relative change observed in this study." (PMID 35071050, 2021). "The number of infected cells (intracellularly stained with anti-HIV-Gag antibody) peaked five days after infection, and a concomitant increase in lysosomal destabilization, as demonstrated by the release of cathepsin D (B and L, not shown), was observed." (PMID 23658518, 2013). "S or CTsd alone are not very effective; however, in combination, they reduce the infection rate to 17 percent, an efficacy far greater than when they are singly imposed." (PMID 18596963, 2008). "Moreover, while cathepsin D/E activity was not affected by infection, the activity of lysosomal cathepsin S was significantly reduced in HSV-1–infected LUHMES cells, suggesting a defect in lysosomal proteolytic function." (PMID 41596294, 2026). "This secretion is not specific to cathepsin B but rather is observed for several lysosomal proteins, which show unchanged intracellular abundance, including cathepsin D. This is likely a host response to infection rather than an active pathogenesis mechanism employed by C. burnetii." (PMID 40274809, 2025). "After infection with the recombinant lentiviruses over-expressing NSF, the OGD-created impairment of autophagic flux was greatly restored, as reflected by decreased autophagic cargoes of LC3-II, insoluble p62 and ubiquitinated proteins, accompanied by increased CTSD." (PMID 39155286, 2024). "The results showed that at 12–24 h of infection the % of co-localization of the WT FCPs with both LAMP-2 and cathepsin-D positive compartments did not change from the 2 h time point in the CDC27, USP22, or PI4KCA RNAi-treated cells." (PMID 20552012, 2010). "The levels of CTSD seemed to be slightly increased in the U937 cells after infection with the 201 strain, and the levels of CTSZ showed no significant alterations during the infection." (PMID 31069175, 2019). "Phagosomes of MH-S cells containing pre-swollen conidia of either A. fumigatus or A. terreus successfully underwent fusion with lysosomes 3 h and 8 h (data not shown) after infection as indicated by the presence of LAMP-1 and Cathepsin D, characterizing a mature phagolysosome." (PMID 22319619, 2012). "In this study we demonstrate that the absence of cathepsin D significantly inhibits the T cell response to two epitopes of P. chabaudi cabaudi MSP1 antigen, either after processing of infected erythrocytes by bone marrow derived DC in vitro, or by splenic DC during in vivo infection." (PMID 22053177, 2011).
neurodegenerative disease (36 papers, 2008 to 2025). A disorder of the central nervous system characterized by gradual and progressive loss of neural tissue and neurologic function. "Cathepsin D is a lysosomal aspartyl protease that has been linked to several neurodegenerative diseases, including AD and PD." (PMID 40713630, 2025). "Cathepsin D is a lysosomal protease important for the degradation of various substrates, as is the neurodegenerative diseases-associated protein α-synuclein." (PMID 38607042, 2024). "The association between genetic variations of cathepsin D and neurodegenerative diseases has been reported." (PMID 33445607, 2021). "CTSD has been implicated in multiple neurodegenerative diseases and was previously demonstrated to associate with PGRN, which promotes CTSD maturation and activity." (PMID 34344440, 2021). "Nevertheless, the question about the role and impact of CTSD mutations on the pathology of neurodegenerative diseases is still elusive." (PMID 33681191, 2021). "The importance of cathepsin D for the normal functioning of CNS is emphasized by many neurodegenerative diseases caused by cathepsin D deprivation." (PMID 34198733, 2021). "In neurons, loss of CTSD leads to lysosomal dysfunction and accumulation of different cellular proteins implicated in neurodegenerative diseases." (PMID 34070492, 2021). "In this study, we characterize eleven CTSD variants associated with neurodegenerative diseases by analyzing their cellular localization, maturation, enzymatic activity, a-syn degradation capacity and structural properties." (PMID 33681191, 2021). "Mutations in CTSD gene, which encodes the Cathepsin D protein involved in lysosomal protein degradation, can lead to protein metabolism disorders and are associated with neurodegenerative diseases such as AD and PD." (PMID 40520613, 2025). "Multiple genetic variants within the CTSD gene have been linked to neurodegenerative diseases." (PMID 39823474, 2025). "Cathepsin D (CatD) is a lysosomal aspartyl protease that degrades both Aβ and tau in vitro and is strongly implicated in the pathogenesis of AD and multiple other neurodegenerative diseases." (PMID 32631408, 2020). "In addition to their roles in neuronal development and synaptic plasticity, cathepsins, particularly cathepsin D, have been linked to neurodegenerative diseases such as AD and Parkinson's disease (PD), in which they participate in the processing of pathological proteins." (PMID 39122455, 2024). "Decreased expression of CTSD in neurons results in the accumulation of proteins and impairs lysosomal activity, particularly in neurodegenerative diseases such as ALS." (PMID 38135852, 2024). "Whole body CtsD gene knockout (CtsD-KO) mice are born normally but develop a rapidly progressive neurodegenerative disease-like phenotype with seizures, small intestine necrosis, and premature death at approximately postnatal day 264,5." (PMID 35804072, 2022). "The expression of both hexosaminidase A and cathepsin D is upregulated in neurodegenerative diseases." (PMID 25976368, 2016). "Therefore, the alteration of cathepsin D activity is detrimental for these cells, leading to the onset and progression of several neurodegenerative diseases." (PMID 40243477, 2025). "Cathepsin D is a lysosomal protein that contributes to autophagy in many neurodegenerative diseases, and its levels are elevated in the CSF of patients with AD, suggesting it could be a potential biomarker of autophagy." (PMID 40507855, 2025). "It increases the production of cathepsin D, which helps to prevent this disease from occurring since it has been shown that many neurodegenerative diseases arise when there are low levels of cathepsin D or it is inactive, causing failures in one of the genes that produces this disease." (PMID 36141396, 2022). "Recently, the relation of cathepsin D with neurodegenerative diseases is getting great attention." (PMID 35804072, 2022).
neurodegenerative disease (continued). "Based on the role played by cathepsin D in age-associated neurodegenerative diseases, as in NCL, cathepsin D may be a promising therapeutic target." (PMID 36142612, 2022). "In particular, several proteins (i.e., amyloid precursor, tau, α-synuclein, and lipofuscin), whose altered processing is associated with neurodegenerative diseases, are physiologic cathepsin D substrates and accumulate if they are not efficiently degraded." (PMID 36142612, 2022). "Considering these results, we propose thatt the CtsD-CKO mouse is a useful mouse model to investigate the contribution of cathepsin D to the early phases of neurodegenerative diseases in relation to lipofuscins, proteinopathy-related proteins and activation of microglia and astrocytes." (PMID 35804072, 2022). "In neurodegenerative disease, abnormal accumulation of neuronal proteins (e.g., the amyloid precursor, α-synuclein, and huntingtin) are due to diminished or abolished activity of Cathepsin D." (PMID 31091796, 2019). "Many altered neuronal proteins that hallmark neurodegenerative diseases (such as the amyloid, α-synuclein, and huntingtin) are physiologic substrates of cathepsin D and would abnormally accumulate if not efficiently be degraded by this enzyme." (PMID 29183303, 2017). "Moreover, cathepsin D plays a key role in the pathogenesis and progression of human neurodegenerative diseases." (PMID 29183303, 2017). "In patient-derived fibroblasts, biochemical analyses indicated that mutant CTSD is produced but not efficiently processed into the mature form, linked to autophagic dysfunction, may predispose neurodegenerative diseases in late adulthood." (PMID 34070492, 2021). "It has also been reported that the potential subtle effects of the c.C224T polymorphism (p.Ala58Val) of the CTSD gene on lysosomal function may not be associated with childhood‐onset neurodegenerative diseases." (PMID 34331747, 2021). "Therefore, developing therapies that target CTSD and other components of the lysosomal pathway holds promise for treating ALS and other neurodegenerative diseases." (PMID 38135852, 2024).
prostate (4 papers, 2006 to 2025). "Thrombospondin-1 (THBS1) and cathepsin D (CTSD) are two glycoproteins identified to be associated with prostate carcinogenesis by mass spectrometry-based proteomics." (PMID 39081487, 2024). "At the morphological level lysosomes appeared more prominent in AEP-null kidney PTC and cathepsin D (CtsD) staining was more intense indicating accumulation of undegraded material and/or increased expression of lysosomal proteins." (PMID 30559339, 2018).
bacterial infection (3 papers, 2018 to 2024). "Analysis of lysosome membrane damage showed that cathepsin D, an enzyme present inside lysosomes, was released by ≈50% in cytosol after bacterial infection." (PMID 29600279, 2018). "We further verified the induction of CtsD protein in MTX-treated RAW264.7 cells in both the presence and absence of bacterial infection by Western blotting." (PMID 36812322, 2023).